HMGB3 (high mobility group box 3)
Diseases named in the same sentence as HMGB3 in open-access papers (continued):
Sharing a sentence is not in itself a finding about the gene and the disease.
lung adenocarcinoma (5 papers, 2021 to 2025). A carcinoma that arises from the lung and is characterized by the presence of malignant glandular epithelial cells. "Overexpression of HMGB3 reverses the inhibitory effects of miR‐5195‐3p on proliferation and metastasis in lung adenocarcinoma cells." (PMID 41354099, 2025). "The prescreening strategy using CEACAM5 and HMGB3 expression facilitates tumor-centric scRNA-seq analyses of lung adenocarcinoma." (PMID 36397035, 2022). "For example, in the Hou Lung dataset, a 5.974-fold increase in HMGB3 mRNA expression was identified in lung adenocarcinoma (LUAD) tissues vs. normal lung tissue (p = 3.38E-15)." (PMID 35923467, 2022). "We found that CEA cell adhesion molecule 5 (CEACAM5) and high mobility group box 3 (HMGB3) were reliable markers for RT-PCR-based prescreening of tumor cells in lung adenocarcinoma." (PMID 36397035, 2022). "Altogether, these results suggest that real-time PCR screening of CEACAM5 and HMGB3 can be used to confirm the presence of tumor cells in lung adenocarcinoma specimens of both tissue and lymph node origin, as well as in cDNAs and single-cell or nuclear RNA sequencing libraries." (PMID 36397035, 2022). "In lung adenocarcinoma, miR-5195-3p can complementarily bind to the 3′UTR of HMGB3, whereby an increased level of miR-5195-3p expression leads to a decrease in HMGB3 expression." (PMID 39062899, 2024).
lung squamous cell carcinoma (5 papers, 2020 to 2024). "On the other hand, RNA binding protein TAF15, acting as an RNA stabilizer, is reported to be recruited by lncRNA PITPNA‐AS1 to stabilize HMGB3 mRNA, enhancing proliferation and migration of lung squamous cell carcinoma cells." (PMID 39715205, 2024). "PITPNA-AS1 recruited TAF15 to maintain HMGB3 in lung squamous cell carcinoma cells." (PMID 34496348, 2021). "In lung squamous cell carcinoma, PITPNA-AS1 was also observed to boost tumor cells' proliferating and migrating processes via recruiting TAF15 for stabilizing HMGB3 mRNA." (PMID 34055841, 2021).
esophageal squamous cell carcinoma (4 papers, 2018 to 2025). Esophageal squamous cell carcinoma (ESCC) is a type of esophageal carcinoma (EC) that can affect any part of the esophagus, but is usually located in the upper or middle third. "For example, increased expression of HMGB3 was found in esophageal squamous cell carcinoma, which predicted worse outcome." (PMID 32131767, 2020).
hepatocellular carcinoma (4 papers, 2016 to 2024). A malignant tumor that arises from hepatocytes. "Knockdown of HMGB3 in the hepatocellular carcinoma cell line suppressed cell proliferation and migration." (PMID 30343649, 2018). "After analyzing The Cancer Genome Atlas data of 371 patients with hepatocellular carcinoma, we identified HMGB3 to be upregulated in human hepatocellular carcinoma tissue." (PMID 30343649, 2018). "Here, we report that HMGB3, which is suppressed by miR-200b, contributes to cell proliferation and migration in human hepatocellular carcinoma." (PMID 30343649, 2018). "Our findings suggest HMGB3 may serve as an important oncoprotein whose expression is negatively regulated by miR-200b in hepatocellular carcinoma." (PMID 30343649, 2018). "However, the expression and the role of HMGB3 in human hepatocellular carcinoma remain unknown." (PMID 30343649, 2018). "Similarly, in hepatocellular cancer, in vitro and in vivo treatment with vorinostat or panobinostat triggers let-7b upregulation, leading to the downregulation of BCL-XL, TRAIL (tumor necrosis factor (ligand) superfamily, member 10) or the oncoprotein HMG2A (high mobility group box 3)." (PMID 31658720, 2019).
laryngeal squamous cell carcinoma (4 papers, 2021 to 2023). A squamous cell carcinoma that arises from the larynx. "LINC00319 stimulates CD133+CD144+ TU177 cell self-renewal ability and tumorigenicity by upregulating HMGB3 via recruitment of E2F1 in laryngeal squamous cell carcinoma." (PMID 37328851, 2023).
prostate adenocarcinoma (4 papers, 2021 to 2024). "Thus, HMGB3/SOX9-mediated NANOG induction may lead to increased viability of prostate adenocarcinoma cells." (PMID 39062899, 2024). "Recently, a new mechanism for regulating the development of prostate adenocarcinoma (PCa), which involves the deregulation of SOX9, HMGB3, and NANOG, was discovered." (PMID 39062899, 2024). "HMGB3 cooperates with SOX9 to induce NANOG transactivation, promote the expression of oncogenic genes downstream of NANOG, and further enhance prostate adenocarcinoma cell survival and migration." (PMID 37328851, 2023).
Sepsis (4 papers, 2021 to 2025). Sepsis is defined as life-threatening organ dysfunction caused by a dysregulated host response to infection. "The authors showed that the extent of sepsis-induced lung injury is regulated by the miR-128-3p/HMGB3 axis." (PMID 39062899, 2024). "MiR-424-5p binds to HMGB3 in acute injury of human pulmonary alveolar epithelial cells stimulated by lipopolysaccharides and in patients with sepsis-induced lung damage." (PMID 39062899, 2024). "Next, qRT-PCR was conducted to analyze the SNHG16/miR-128-3p/HMGB3 expression in sepsis-mediated ALI rats." (PMID 34092219, 2021). "As a result, SNHG16 and HMGB3 were up-regulated, while miR-128-3p was down-regulated in sepsis-induced ALI both in vivo and in vitro." (PMID 34092219, 2021). "In contrast, a sepsis model in BEAS-2B was induced with lipopolysaccharide (LPS) to verify the effects of SNHG16/miR-128-3p/HMGB3 on lung epithelial cell viability and apoptosis." (PMID 34092219, 2021). "down-regulating SNHG16 alleviates the sepsis-mediated ALI by regulating miR-128-3p/HMGB3." (PMID 35720285, 2022). "Interestingly, our study found that SNHG16 and HMGB3 were up-regulated in sepsis model with ALI, while miR-128-3p was downregulated." (PMID 34092219, 2021). "Overall, down-regulating SNHG16 alleviated the sepsis-mediated ALI by regulating miR-128-3p/HMGB3." (PMID 34092219, 2021). "Therefore, we speculate that there’s a regulatory axis of SNHG16/miR-128-3p/HMGB3 in sepsis-mediated ALI." (PMID 34092219, 2021). "However, whether HMGB3 plays a role in sepsis-induced organ inflammation remains elusive." (PMID 34092219, 2021).
lymph node metastasis (3 papers, 2022 to 2024). "HMGB3 expression levels were also positively associated with lymph node metastasis and drug resistance." (PMID 35332131, 2022). "Our previous study revealed that high HMGB3 levels are associated with poor prognosis and lymph node metastasis in patients with high-grade serous ovarian carcinoma; however, the role of HMGB3 in EOC proliferation and metastasis remains unknown." (PMID 37328851, 2023). "In our previous study, we found that high HMGB3 expression predicted poor prognosis and lymph node metastasis in patients bearing HGSOC." (PMID 37328851, 2023).
acute myeloblastic leukemia (2 papers, 2021 to 2023). "Besides, overexpression of HMGB3 has been linked to acute myeloblastic leukemia and metastatic breast cancers." (PMID 33842327, 2021). "HMGB3 was found to be overexpressed in a variety of cancers, including breast invasive carcinoma, sarcoma, skin cutaneous melanoma, ovarian serous cystadenocarcinoma, and acute myeloid leukemia." (PMID 36936912, 2023).
bladder tumor (2 papers, 2022 to 2023). "The percent of patients with CitH3+HMGB3+ and CitH3+MPO+ was further quantified in the two breast, two lung as well as one bladder tumor tissue arrays." (PMID 36973439, 2023).
breast tumors (2 papers, 2013 to 2022). "The expression of HMGB3 mRNA was quantified in the 33 human breast tissues and was elevated in the metastatic group and in the breast tumors compared to unaffected adjacent benign tissue." (PMID 24098490, 2013).
head and neck squamous cell carcinoma (2 papers, 2021 to 2024). A squamous cell carcinoma that arises from any of the following anatomic sites: lip and oral cavity, nasal cavity, paranasal sinuses, pharynx, larynx, and salivary glands. "After analyzing with the UALCAN database, we observed a high expression of HMGB3 in head and neck squamous cell carcinoma." (PMID 39390359, 2024).
latent infection (2 papers, 2018 to 2021). "Altogether, these data are consistent with direct binding of SRP14, HMGB3 as well as PTB to MS RNA highlighting a potential role of these RNA binding proteins in controlling Tat expression during latent infection." (PMID 34194479, 2021).
myocardial ischemia (2 papers, 2024 to 2026). A disorder of cardiac function caused by insufficient blood flow to the muscle tissue of the heart. "Myocardial injury upregulated the mRNA levels of HMGB3, HIF1α, p65, Reg1α, Reg3γ, and COL18a1 on the third and seventh day in the left anterior descending coronary artery ligation model of myocardial ischemia compared to sham animals." (PMID 38397916, 2024). "This study discovered that HMGB3 plays a dual role during the progression of myocardial ischemia and infarction, as it plays a pro-inflammatory role and improves cardiac function during the cardiac remodeling phase." (PMID 38397916, 2024).
sarcoma (2 papers, 2023 to 2024). A usually aggressive malignant neoplasm of the soft tissue or bone. "Finally, a prognostic model for sarcoma patients was constructed using six hub genes: risk score = 0.05 × VEGFA + 0.25 × HMGB3 + 0.22 × FASN + 0.40 × RCC1 + 0.46 × NETO2-0.10 × BIRC5." (PMID 38240704, 2024). "As far as we know, the function of HMGB3, FASN and RCC1 in sarcoma has not been reported." (PMID 38240704, 2024).
serous ovarian carcinoma (2 papers, 2022 to 2023). "In the current study, we clarified that HMGB3 was aberrantly overexpressed in high-grade serous ovarian carcinoma (HGSOC) tissues, and high HMGB3 levels indicated shorter overall survival and drug resistance in HGSOC." (PMID 35332131, 2022). "However, the expression pattern and clinicopathological characteristics of HMGB3 in high-grade serous ovarian carcinoma (HGSOC) have not been reported." (PMID 35332131, 2022).
amyotrophic lateral sclerosis (1 paper, 2015). Amyotrophic lateral sclerosis (ALS) is a neurodegenerative disease characterized by progressive muscular paralysis reflecting degeneration of motor neurons in the primary motor cortex, corticospinal tracts, brainstem and spinal cord. "miR-206 has exhibited its regulation of fibroblast growth factor, Hmgb3 and HIF-1α/Fhl-1 pathways in amyotrophic lateral sclerosis, muscle regeneration and pulmonary hypertension, respectively." (PMID 25816284, 2015).
bacterial Sepsis (1 paper, 2025). "As research progresses, it may become possible to design novel therapies specifically targeting HMGB1, HMGB3, and their associated pathways to alleviate the impact of bacterial Sepsis-Associated ALI." (PMID 40842982, 2025).
colitis (1 paper, 2025). Inflammation of the colon. "The hsa_circ_0004662/miR‐532/HMGB3 axis was further validated in a DSS‐induced colitis mouse model, where hsa_circ_0004662 knockdown attenuated inflammation and tissue damage." (PMID 40099942, 2025).
collecting duct renal cell carcinoma (1 paper, 2023). "HMGB3 has also been identified as a specific regulator of the CSC cluster in collecting duct renal cell carcinoma." (PMID 38149239, 2023).
HIV-1 infection (1 paper, 2021). The type species of lentivirus and the etiologic agent of acquired immunodeficiency syndrome (AIDS). "The effect of SRP14 and HMGB3 KD on use of SA3 is consistent with the effects of these proteins on latent and productive infection, suggesting an important role of these proteins in Tat mRNA processing and regulation of HIV-1 infection." (PMID 34194479, 2021).
influenza (1 paper, 2023). An acute viral infection of the respiratory tract, occurring in isolated cases, in epidemics, or in pandemics; it is caused by serologically different strains of viruses (influenzaviruses) designated A, B, and C, has a 3-day incubation period, and usually lasts for 3 to 10 days. "Additionally, genes involved in cell processes and cytoskeletal structural elements were upregulated in activated cTfh cells compared to resting cells following influenza vaccination: ELMO2, ACTG1, STMN1, ANP32B, UCP2, and HMGB3." (PMID 37063867, 2023).
metastatic tumor (1 paper, 2022). "HMGB3 from the black module has a significant positive correlation with metastasis (p < 0.001), and HMGB3 was significantly overexpressed in cluster 1 (CTCs and metastatic tumor cells) as compared to cluster 0 (PT cells) (p < 0.001)." (PMID 35754798, 2022).
microcephaly (1 paper, 2023). A congenital or acquired developmental disorder in which the circumference of the head is smaller than normal for the person's age and sex. "According to GO analysis, these genes are associated with either abnormal hematopoiesis (Aurkb, Fen1, Hrob, Kif20a, Rad51ap1 and Tsr2) or microcephaly (Casc5, Hmgb3, Ncaph and Wdr62), or both (Fanca and Trip13)." (PMID 37661832, 2023).
muscular dystrophy (1 paper, 2012). Muscular dystrophy (MD) refers to a group of more than 30 genetic diseases characterized by progressive weakness and degeneration of the skeletal muscles that control movement. "Identification of genes controlled by myomiR-206 through Hmgb3 can be instrumental to explain the molecular mechanisms involved in myomiR-206 mediated muscle regeneration in muscular dystrophy and muscle damage." (PMID 22912879, 2012).
neuroblastoma (1 paper, 2021). Neuroblastoma (NB) is the most common solid, extracranial childhood tumor. "Taken together, these data indicated that HMGB3 plays a critical role in neuroblastoma tumorigenesis." (PMID 34988076, 2021).
pancreatic carcinoma (1 paper, 2022). "Furthermore, through the GEPIA 2 database, HMGB3 was also found to be highly expressed in pancreatic carcinoma compared with the matched normal tissue and the normal pancreatic data from the Genotype-Tissue Expression (GTEx) portal." (PMID 35754798, 2022). "Moreover, protein expression levels were similarly compared using the HPA database, and the low protein expression levels of HMGB3 were revealed in normal pancreatic tissues, while medium protein expression levels of HMGB3 were revealed in pancreatic cancer tissues." (PMID 35754798, 2022).
renal carcinoma (1 paper, 2020). A carcinoma arising from the epithelium of the renal parenchyma or the renal pelvis. "This regulates cell growth, differentiation, apoptosis and cancer progression by directly binding to miR-615-3p and acting effectively as an endogenous sponge to modulate the suppression of IGF-2 in renal carcinoma or the expression of high mobility group box 3 (HMGB3) in NSCLC cells." (PMID 32605009, 2020).
silicosis (1 paper, 2024). Silicosis is a respiratory disease caused by breathing in (inhaling) silica dust. "High expression of collagen I indicated that we had successfully constructed a silicosis mouse model and that the protein expression of HMGB3 was increased in the lung tissues of mice with silicosis." (PMID 38454505, 2024). "We next investigated the expression of the HMGB3 protein in mice with silicosis." (PMID 38454505, 2024). "Therefore, the identification of exosomal HMGB3 as an important inflammatory mediator might provide a new strategy for attenuating inflammation in the early stage of silicosis." (PMID 38454505, 2024).
thyroid cancer (1 paper, 2024). "Inhibition of HMGB3 expression reduces cell viability, promotes apoptosis and cell cycle arrest, and suppresses migration and invasion of thyroid cancer cells." (PMID 39062899, 2024). "Moreover, SYT7 was found to interact with BRCA1 and negatively regulate the ubiquitination of HMGB3, thereby stabilizing this protein and promoting thyroid cancer progression." (PMID 39062899, 2024). "Cytoplasmic HMGB3 activates nucleic acid-mediated TLR3/NF-κB signaling, and extracellular HMGB3 interacts with the transmembrane receptor triggering receptor expressed on myeloid cells (TREM1 and CD354) in thyroid cancer." (PMID 39062899, 2024). "Thus, HMGB3 could be used as a potential circulating biomarker and therapeutic target in PTC and thyroid cancer." (PMID 39062899, 2024).
triple-negative breast carcinoma (1 paper, 2022). An invasive breast carcinoma which is negative for expression of estrogen receptor (ER), progesterone receptor (PR), and human epidermal growth factor receptor 2 (HER2). "Additionally, we discovered that HMGB3 expression levels were substantially greater in the basal-like subtype than in the nonbasal-like subtype (p<0.0001), and individuals with triple-negative breast cancer (TNBC) also showed the same pattern of change (p<0.0001)." (PMID 36620553, 2022).